CUL4A (cullin 4A)
Diseases named in the same sentence as CUL4A in open-access papers (continued):
Sharing a sentence is not in itself a finding about the gene and the disease.
tumor (continued). "Moreover, its knockdown also reversed the facilitating impact of CUL4A expression on tumor growth and declined the expression levels of proliferation-, migration-, and NF-κB signaling-related protein in the tumor." (PMID 35333690, 2022). "NPC cells and tumor-bearing mice were cultivated to explore the role and mechanism of CUL4A in NPC." (PMID 35333690, 2022). "Therefore, this study selected NPC cells and constructed tumor-bearing mouse model to explore the role and mechanism of CUL4A in NPC." (PMID 35333690, 2022). "In addition, its knockdown likewise reversed the facilitating impact of CUL4A expression on tumor growth and declined the expression levels of proliferation-, migration-, and NF-κB signaling-related protein in the tumor." (PMID 35333690, 2022). "Our previous findings suggest the importance of CUL4A in tumor progression." (PMID 34257560, 2021). "CUL4A promotes autophagy, and exhibits significantly higher autophagic flux which affects the proliferation of iCCA cells; these effects correlated with advance tumor stage and poor prognosis." (PMID 34257560, 2021). "CUL4A was shown to regulate the termination of autophagy in a physical process and our previous study demonstrated the positive correlation between CUL4A expression and tumor invasion and poor prognosis of iCCA." (PMID 34257560, 2021). "In the present study, we elucidated the clinical effects of CUL4A in iCCA that are probably mediated through intact activated autophagy, which affects the proliferation of iCCA cells; these effects correlated with advance tumor stage and poor prognosis." (PMID 34257560, 2021). "Knockdown either CUL4A/4B or DDB1 significantly inhibits tumor cell growth in vitro and in vivo." (PMID 32140073, 2020). "Our previous study found that CUL4A can regulate EMT of tumor cells." (PMID 31060565, 2019). "The authors also suggested that directly targeting CUL4A with the purpose of disrupting this oncogenic signaling pathway might lead to tumor-inhibitory effects." (PMID 28576144, 2017). "Other tumor-related signal-transduction pathways are also modulated by CUL4A expression." (PMID 28576144, 2017). "In addition to tumor size, resection margin, and tumor stage, CUL4A overexpression was shown to be an independent unfavorable DFS predictor (P = 0.045)." (PMID 28576144, 2017). "Overexpression of CUL4A is correlated with tumor recurrence and promotes tumor progression." (PMID 28576144, 2017). "Significant growth inhibition by gemcitabine was observed in Cul4A knockdown H460 and H157 tumours." (PMID 26969027, 2016). "It is possible that other signalling pathways (i.e. RAS, EGFR, Notch) may also be involved in Cul4A-mediated tumour growth." (PMID 26218750, 2015). "Ectopic CUL4A expression in homograft tumor promoted tumor growth in mice." (PMID 26593394, 2015). "Overexpressed Cul4A may also contribute to genomic instability by degrading replication licensing factor CDT1 in tumour cells." (PMID 26218750, 2015). "Increased Cul4A is positively correlated with distant metastasis in various human tumours." (PMID 26218750, 2015). "Collectively, our data demonstrate that increased CUL4A expression correlates with the progression of HCC and CUL4A might be involved in promoting tumor growth and metastasis." (PMID 26593394, 2015). "Moreover, we performed immunohistochemistry analysis in 78 NSCLC specimens and 56 normal lung tissues and found that CUL4A level was higher in 87.2% of tumor samples (68 of 78) than that in normal lung tissue." (PMID 25413624, 2014). "Our results indicate that CUL4A might play a central role in the oncogenic process by modulating the expression of a number of oncogenes and tumor suppressors." (PMID 24870930, 2014). "In addition, p21, the master effector of multiple tumour suppressor pathways, has been shown to accumulate in Cul4A deleted MEFs upon UV irradiation leading to prolonged G1/S arrest." (PMID 24522884, 2014).
tumor (continued). "It has been shown that CUL4A could contribute to tumor malignancy mediating the activity of tumor suppressors and thus, altering cell cycle checkpoints." (PMID 19995430, 2009). "Thus, CUL4A contributes to both tumor initiation and progression, and understanding the mechanisms associated with progression, metastasis, and prognosis might be valuable to serve CUL4A as a prognosis biomarker and a target for drug development." (PMID 31860954, 2019). "In addition, our study also found that CUL4A can regulate EMT of tumor cells." (PMID 31060565, 2019). "Consequently, these results identified that lncRNA uc.134 activates Hippo kinase signaling by blocking CUL4A, suggesting that it may serve as a tumor suppressor and prognostic biomarker in HCC." (PMID 28420424, 2017). "Via diverse substrate receptors, CUL4A/B-DDB1 E3 ligases have been associated with the regulation of a wide variety of different cellular functions, such as DNA replication and damage recognition, cell cycle control, steroid receptor activation, and tumor suppression." (PMID 26021757, 2015). "Whether the Hh/Gli1 pathway is involved in Cul4A-mediated EMT in tumour cells is unknown." (PMID 26218750, 2015). "Thus, CUL4A can contribute to tumor development by the way of participating in histone methylation." (PMID 26460955, 2015). "Transcriptomic profiling of TCGA datasets revealed significant up-regulation of CUL1, CUL2, CUL4A, CUL4B, CUL5, CUL7, and CUL9 in tumor tissues, with higher expression correlating with advanced stage and poorer survival, particularly for CUL5 and CUL7." (PMID 42021323, 2026). "The results showed that transcription of CUL4A and DDB1 was significantly higher in tumor tissue than in normal tissue." (PMID 36481655, 2022). "The tumor volume in the Ov-CUL4A + shRNA-PRMT5 group increased slowly and was tremendously smaller than that in the Ov-CUL4A group on the day of stripping." (PMID 35333690, 2022). "Taken together, this paper indicates that CUL4A promotes the proliferation, migration, invasion of NPC cells, and tumor growth by promoting PRMT5 to activate NF-κB signaling." (PMID 35333690, 2022). "Together, this paper indicated that CUL4A promoted the proliferative, invasive, and migratory aptitude of NPC cells as well as tumor growth by promoting PRMT5 to activate NF-κB signaling." (PMID 35333690, 2022). "Of 133 samples with RNA-seq data available, CUL4A and CCNK expression of the tumor was significantly higher than that in normal tissue." (PMID 36272974, 2022). "Together, these results indicated that CUL4A promoted the proliferative, invasive, and migratory aptitude of NPC cells as well as tumor growth by promoting PRMT5 to activate NF-κB signaling." (PMID 35333690, 2022). "Conclusively, XRCC3, CUL4A, and CSK1E methylation highly correlated with tumor purity (Figure 4SC‐F)." (PMID 32991787, 2020). "Another limitation is the lack of reliable antibodies for protein expression analysis in paraffin tumor samples, which limits the validation of potential biomarkers (e.g., ERCC1 and CUL4A)." (PMID 32365979, 2020). "We also evaluated the effects of knockdown and inhibition of CPCM components on CUL4A/4B expression, ST7 ubiquitination, oncogenic phenotypes, and in vivo tumor growth." (PMID 32140074, 2020). "Gene expression analysis of 4 genes (BRCA1, CUL4A, ERCC1, and ERCC5), involved in the DNA damage repair (DDR) machinery, was performed in 66 surgical tumor samples." (PMID 32365979, 2020). "We assessed the gene expression of CUL4A and CUL4B in 94 tumor tissues collected from MPM patients at diagnosis, surgery or relapse by quantitative real-time PCR (qPCR)." (PMID 33233664, 2020). "In conclusion, this study demonstrates that CUL4A expression was upregulated in NPC tissues, and CUL4A high expression showed a significant correlation with tumor size, lymph node involvement, distant metastasis, and clinical stage." (PMID 31860954, 2019).
tumor (continued). "High levels of CUL4A were found in HCC tissues and closely correlated with tumor differentiation grade and metastasis." (PMID 26593394, 2015). "To further investigate the role of CUL4A in HCC development, we measured the growth of H22 tumor homografts in BALB/c mice where CUL4A expression was modulated." (PMID 26593394, 2015). "A recent study showing interaction of CUL4A with p16INK4a promoter establishes another link with the cell cycle, because CDK inhibitor p16INK4a is known for its functions in tumour suppression and cell ageing processes." (PMID 24522884, 2014). "We propose that CUL4A and TFDP1 are likely the driver genes for this genomic amplification, leading higher tumor aggressiveness through deregulation of cell cycle." (PMID 19995430, 2009). "Furthermore, the levels of CUL4A, PRMT5, nuclear p65, total p65, and IκBα in the tumor were assessed by western blotting." (PMID 35333690, 2022). "Our results confirmed that LINC01468 increases CUL4A-mediated degradation of SHIP2, by which SHIP2 negatively regulates PI3K/Akt, thereby promoting lipogenesis and HCC progression; thus, SHIP2 functions as a tumor suppressor in NAFLD-HCC." (PMID 36344496, 2022). "Pharmacologic inhibition of EZH2, CUL-4A, or the proteasome can increase the steady-state level of DLC1 protein, whose tumor suppressor activity is further increased by AKT and/or SRC kinase inhibitors, which reverse the direct phosphorylation of DLC1 by these kinases." (PMID 34862367, 2021). "However, deletion of CUL4A and CUL4B in mouse embryonic fibroblasts, as well as cultured tumor cells, results in growth retardation, suggesting that the CRL4 E3 ligase activity plays an essential role in growth." (PMID 34604860, 2021). "Since NSC1892 specifically targeted the CUL4A/4B-DDB1 interactions, we speculated that it should also be effective to inhibit the cell growth of other CUL4A- or CUL4B-overexpression tumor cells, not only CRC cells." (PMID 32140073, 2020). "Representative examples of staining showed that there was no CUL4A expression in tumor-adjacent tissues." (PMID 31860954, 2019). "In addition, Cul4A knockdown increases the expression of KLF10, cyclin-dependent kinase inhibitor p21/WAF1, and TGF-β1, which play a role as tumor suppressors." (PMID 29799499, 2018). "CUL4A may also play a crucial role in the regulation of PAQR3 (progestin and adipoQ receptor family member III), a newly discovered tumor suppressor that exerts its biological function through negative regulation of the oncogenic Raf/MEK/ERK signaling." (PMID 29594129, 2018). "Compared to CUL4A, reports about the relationship between CUL4B and tumor are lack." (PMID 26460955, 2015). "However, CUL4A expression was significantly increased in HCC tissues, when compared with paired adjacent non-tumor tissues." (PMID 26593394, 2015). "CUL4A expression was not correlated with gender, age or tumor subtype but statistically significantly correlated with NSCLC clinical stages." (PMID 25413624, 2014). "Besides, dysregulation in post-transcriptional modifications, like ubiquitination enzymes (HUWE1, CUL4A, TRIM25, etc.)and deubiquitination enzymes (USP7, USP10, USP24, etc.)in these PTC tumor samples may also lead to the low consistency." (PMID 38609408, 2024). "FBXW5 was reported to interact with cullin 4A–RING ubiquitin ligase–DNA damage-binding protein 1 (CUL4A–DDB1) and act as a major substrate recognition component for the ubiquitination and degradation of deleted in liver cancer 1 (DLC1), which promotes tumor progression." (PMID 35210431, 2022). "In addition, treatment with a CUL-4A inhibitor or a proteasome inhibitor can substitute functionally for EZH2 inhibition both in increasing the steady-state level of DLC1 protein and in cooperating with the two kinase inhibitors for tumor treatment." (PMID 34862367, 2021). "Thus, CUL4A, acting as an oncogene, significantly contributes to not only tumor initiation, but also progression." (PMID 26593394, 2015).
tumor (continued). "In addition a set of 15 proteins that participate in the antitumor immune response such as the tumor suppressors PSMB9, ERAP1 and TAP1 or the interferon-stimulated genes IFIT1 and MX1 were found down-regulated in CUL4A-overexpresing cells and up-regulated in CUL4A-silencing models." (PMID 24870930, 2014). "However, CUL4A expression was not statistically different based on tumor differentiation, indicating that CUL4A may not participate in the differentiation process." (PMID 26840256, 2016). "CUL4 paralogs (CUL4A and CUL4B) were upregulated in MPM tumor specimens compared to nonmalignant pleural tissues." (PMID 33233664, 2020).
infection (5 papers, 2012 to 2022). The state of being infected such as from the introduction of a foreign agent such as serum, vaccine, antigenic substance or organism. "Infected Lox-Stop-Lox Cul4A mice (hereafter referred to as Lox-Cul4A) were killed at 8, 12, 16, 20, 24 and 24 wk post-infection." (PMID 26104890, 2015). "Here both exogenous UNG2–2HA and endogenous UNG2 were depleted upon infection however only the depletion of the exogenous protein was blocked by DN CUL4A and DN UBC12." (PMID 24245672, 2013). "The partial reduction in DCAF1 levels did not affect the infection of the HIV-1 Vpr+ and HIV-1 Vpr+, suggesting that the Vpr-mediated enhancement of infection in HuT/CCR5 cells did not involve the recruitment of the DCAF1/DDB1/Cul4A complex and proteasomal degradation." (PMID 22570689, 2012).
cardiovascular diseases (1 paper, 2019). "However, both the function of Cul4a in the cardiovascular disease and its role in myocardial injury caused by oxidative stress are still unclear." (PMID 31178959, 2019). "In addition, although our study is the first to report that Cul4a is involved in oxidative stress-induced myocardial injury, whether Cul4a is associated with other cardiovascular diseases is still unclear." (PMID 31178959, 2019). "However, the role of Cul4a in cardiovascular disease has been little reported." (PMID 31178959, 2019).
CUL4A also shares sentences with these, for which no sentence is quoted: adrenocortical carcinoma (3 papers); pleural mesothelioma (3); lung adenocarcinoma (2); medulloblastoma (2); squamous cell carcinoma (2); adenocarcinoma (1); anemia (1); bipolar disorder (1); childhood medulloblastoma (1); endometrial cancer (1); Fanconi anemia (1); head and neck squamous cell carcinoma (1); HIV-1 infection (1); Hypertension (1); intrauterine growth retardation (1); kidney (1); latent infections (1); leukodystrophy (1); liver disorder (1); liver fibrosis (1); meningioma (1); mucinous adenocarcinoma (1); oral squamous cell carcinoma (1); pancreatic cancer (1); papillary thyroid carcinoma (1); pheochromocytoma (1); pituitary adenomas (1); renal cell carcinoma (1); Sepsis (1); serous adenocarcinoma (1).
A further 2 diseases each share a sentence with CUL4A in 1 paper.